MMP9 (matrix metallopeptidase 9)
Diseases named in the same sentence as MMP9 in open-access papers (continued):
Sharing a sentence is not in itself a finding about the gene and the disease.
tumor (continued). "Interestingly, after the pH of solid tumours were manually adjusted through intratumoural injections of buffer solution, the quantitative imaging revealed that the activity of MMP‐9 and the pH variation in tumour tissue were well correlated with each other." (PMID 38264683, 2023). "As can be seen in these photographs, MMP-9-positive staining could be observed in both the tumor-like cells (enlarged photograph of black frame) and fibroblast-like spindle cells (enlarged photograph of green frame)." (PMID 37175975, 2023). "MMP9 and other proteases encourage tumor invasion by destroying the ECM." (PMID 37970212, 2023). "Moreover, MMP-2 and MMP-9 participate in angiogenesis, thereby enhancing tumor growth and development." (PMID 38069361, 2023). "Compared to plain C6 cells and non-irradiated pEcad-GVs@C6 cells, irradiated pEcad-GVs@C6 cells had significantly lower expression levels of N-cadherin, MMP9, and Sanil1(mesenchymal markers), all of which play important roles in tumor cell migration and invasion." (PMID 37150786, 2023). "Therefore, we examined the expression of related indicators of the epithelial–mesenchymal transformation (EMT) process (E-cadherin, N-cadherin, vimentin, and MMP9), which are closely related to tumor metastasis." (PMID 37060074, 2023). "In addition, hypoxia dramatically reduces the number of infiltrating TAMs, a barrier against the metastatic HGOS cells, and also favors the production of VEGF and MMP-9 by MDSCs, further promoting tumor growth and invasion." (PMID 36614241, 2023). "A higher expression of MMP9 was observed in 56.2% of cases and the higher expression correlated with the presence of lymph node metastases (p<0.001), an advanced stage of cancer (P <0.001), and grade of the tumor (p=0.003)." (PMID 36756017, 2023). "Subsequent experiments with rP21 on the triple-negative breast cancer cell line MDA-MB-231 in vitro demonstrated that rP21 itself is non-toxic and can inhibit the proliferation, migration, and invasion of tumor cells by adhering to them and reducing the expression of MMP-9 and CXCR4." (PMID 38274735, 2023). "ESM1 can activate the downstream MAPK/ERK signaling pathway by binding to the c-Met membrane receptor of vascular endothelial cells and can promote the expression of HIF1α, VEGFA, MMP9, and other pro-angiogenic factors, thereby promoting tumor angiogenesis and peritoneal metastasis." (PMID 38201620, 2023). "EGCG also reduced intracellular oxidative stress, which may contribute to its suppression of tumor invasion via the downregulation of MMP9 and NF-κB." (PMID 36677584, 2023). "Similarly, protein levels of PCNA, cyclin D1, cyclin E, and MMP-9 decreased, whereas TNFα expression increased in the tumor area of the HCT-116 xenograft in nude mice." (PMID 36979011, 2023). "MMP-9, a member of the matrix metalloproteinases (MMPs) family, could promote tumor metastasis via directly degrading the extracellular matrix." (PMID 36838599, 2023). "The activated MMP-2 and MMP-9 could promote tumor cell movement via degrading collagen type IV of the basement membrane." (PMID 36674771, 2023). "Interestingly, in vivo experiments showed that MMP-9 lead to anti-tumor immune response by inducing neutrophil infiltration." (PMID 37766868, 2023). "Additionally, IL8 and MMP-9, which are known to promote angiogenesis and tumor invasion, were found to be preferentially secreted in M0 and M2 co-culture platforms." (PMID 37835577, 2023). "Notably, when glucose starvation occurs, tumour cells enhance the absorption of glutamine and, at the same time, upregulate matrix metallopeptidase 9 (MMP9) to enhance the metastasis of tumour cells and make them leave the harsh environment faster." (PMID 37108242, 2023). "We hypothesise that the higher MMP-9 level of sEVs observed in patients with a poor prognosis is due to the tumour itself." (PMID 36765669, 2023).
tumor (continued). "Interestingly, the activated TGF-β1 was also able to induce pro-MMP-9 protein expression in metastatic tumor cells, indicating the presence of an additive effect on MMP-9 action after chymase activation." (PMID 37175975, 2023). "MMP-9, the most widely investigated protease in carcinogenetic processes, degrades the extracellular matrix, leading to the migration and invasion of cancerous cells, tumor metastasis, angiogenesis and inflammation." (PMID 37511057, 2023). "By co-staining of MMP9 and CTSK, and K8, we found that MMP9 level was elevated in CTSK-positive cells at the tumor-bone boundary of the miR-182-OE lesions compared with the control group, further confirming the increase of osteoclastogenesis at the tumor-bone boundary." (PMID 37127752, 2023). "Performing comparative studies between different tumours requires examining what factors (e.g., age, gender, surgical resection, recurrence, and therapy) may influence MMP-9 levels of serum-derived sEVs." (PMID 36765669, 2023). "Also, MMP-9 protein levels correlated with tumor malignancy grade, chemotherapy status, and recurrence tendency." (PMID 38138968, 2023). "Hence, MMP-9 is indeed a significant gene in different malignant neoplastic diseases and its multifactorial role can provide more insights into diagnostics and therapeutics in the field of medical oncology." (PMID 37077369, 2023). "Furthermore, elevated MMP-9 in the tumor microenvironment stimulates neovascularization and tumor progression." (PMID 38067195, 2023). "The increased expression of MMP3 may also activate other MMPs, such as MMP1 and MMP9, which can promote tumor cell passage through the basement membrane and lead to invasion and metastasis." (PMID 36412203, 2023). "Therefore, our notion is that HNSCC cells need an additional external stimulus, for example, stromal cells or specific matrix components in the tumor microenvironment, for MMP-9 secretion and activation." (PMID 36674806, 2023). "In agreement with our data, MMP9 was reported to be secreted by lung-residing monocytic myeloid-derived suppressor cells (M-MDSC) prior to metastasis to enhance the lung’s ability of tumor cell entrapment." (PMID 37903851, 2023). "Indeed, they can affect angiogenesis, through the release of VEGF, bFGF and MMP9, and support tumor recurrence and resistance to therapies by stimulating CSCs in iCCA." (PMID 36980187, 2023). "Among the five critical genes previously obtained from survival and molecular docking analysis, MMP9 & MET were the upregulated in tumor samples (COAD and READ), while PDGFRA (COAD and READ) & PTGS2/COX-2 (READ) were downregulated according to the expression analysis by box plots." (PMID 36110531, 2022). "In non-small-cell lung cancer cell lines, lncRNA PVT1 can bind to miR-424-5p to decrease the expression of factors in tumor progression, such as CRAM, MMP-2, MMP-9 and Bcl2, to inhibit growth and increase the expression of Bax, thus suppressing the development of tumor cells." (PMID 35409396, 2022). "PGE2-EP3 signaling induced tumor metastasis and angiogenesis by upregulation of matrix metalloproteinase-9 (MMP-9), which could be suppressed by NSAIDs." (PMID 36545311, 2022). "Additionally, MMP-9 also acts as a functional component of angiogenesis switch during multistage carcinogenesis, where MMP-9 triggers the release of a vascular epidermal growth factor, which accelerates tumor growth." (PMID 35463960, 2022). "Furthermore, MMP9 suppresses anti-tumor immunity modifying several ligands and receptors of the immune signature pathways, including T-cell chemoattractant CXC receptor 3 ligands." (PMID 36211450, 2022). "Furthermore, SCF stimulates mast cells to produce matrix metalloprotease‐9 (MMP‐9) that facilitates the recruitment of other mast cells to the tumour and increases tumour‐derived SCF production in an amplification feedback loop." (PMID 35344301, 2022).
tumor (continued). "Interestingly, the previous study performed on sarcoids confirmed the significant over-expression of both MMP2 and MMP9 genes in the tumor tissue and in cell lines transfected with BPV-1 gene construct." (PMID 35742950, 2022). "Finally, as complex matrix metalloproteinases, MMP-9 is involved in tumor cell invasion and metastasis by degrading extracellular matrix (ECM) components." (PMID 35847356, 2022). "MMP7 is upstream of MMP9 and MMP2 that are extensively implicated in tumor metastasis." (PMID 32761892, 2022). "The rapid proliferation of tumor cells leads to tumor ischemia and hypoxia, which directly stimulates angiogenesis and promotes the secretion of cytokines such as matrix metalloproteinase-9 (MMP9), C-X-C motif chemokine ligand 12 (CXCL12) and Wnt7B by various cells, especially tumor cells." (PMID 35454769, 2022). "MMP-9 is a zinc-dependent peptidase that belongs to the gelatinase subfamily of MMPs, causing degradation of gelatin and collagens during ECM remodeling in both tumor invasion and metastasis." (PMID 35805039, 2022). "Among all MMPs, MMP2 and MMP9 are also the most-studied MMPs in tumour EMT pathogenesis." (PMID 36408277, 2022). "MMP-2 and MMP-9 are the most well-studied and major promoters of tumor cell invasion." (PMID 35204054, 2022). "MMP9, due to its proteolytic activity, plays a key role in tumorigenesis by regulating migration, epithelial-to-mesenchymal transition and survival of cancer cells, induction of immune response, angiogenesis and formation of tumor microenvironment." (PMID 35406619, 2022). "mRNA expression of Mmp9, Egfr and Hmox1 (tumor progression), Timp1 and Timp2 (inhibitors of metalloproteinases) and Hif1α (hypoxia) evaluated in lung homogenates was significantly augmented in LLC-challenged Igf1rfl/fl mice, remaining unaltered in CreERT2 mice." (PMID 35688943, 2022). "Secondly, the TCGA transcriptional expression analyses of G6PD and MMP9 were test results of human ccRCC tumor specimens and normal control kidney tissues, which were different from the detection of mRNA and protein expression levels based on stably transfected cell models." (PMID 34975298, 2022). "Moreover, tumour invasion is often associated with the enhanced synthesis of matrix metalloproteinases (MMPs), among which MMP‐2 and MMP‐9 are of central importance." (PMID 35366056, 2022). "MMP9 is particularly important for tumor invasion and metastasis in that it can degrade ColIV." (PMID 35027925, 2022). "MMP is an extracellular matrix degradation enzyme whose main members MMP-2 and MMP-9 are the most critical proteins involved in tumor cell invasion, so the increased expression of MMPs may increase the invasion and metastasis of malignancies." (PMID 36225172, 2022). "Furthermore, COS can inhibit tumor angiogenesis by inhibiting the expression of matrix metalloproteinase-9 (MMP-9), which in turn inhibits the expression of vascular endothelial growth factor (VEGF)." (PMID 36080631, 2022). "In the MMP-9 transgenic mouse model, overexpression of MMP-9 in the liver of mice significantly increased the susceptibility of transgenic animals to stimulator-induced carcinogenesis and tumor development." (PMID 36432152, 2022). "Besides, matrix metalloproteinases (MMPs), especially MMP-2 and MMP-9, are highly expressed in a variety of tumor tissues and play an important role in the development of tumors." (PMID 35979035, 2022). "Lastly, MMP9 can be also pro-tumour along with MMP2, and both of them are involved in metastasis." (PMID 35406451, 2022). "MMP9 is a metalloproteinase capable of cleaving several proteins present in the extracellular matrix to regulate matrix remodeling and, in the context of cancer, increase the proliferation, migration, and invasion of tumor cells to other tissues." (PMID 35741003, 2022). "Since IL-1β is known to promote MMP-9 production in tumor cells, ILC2 may instigate ECM remodeling by PMN-MDSC activation during the early stages of metastasis." (PMID 35805039, 2022).
tumor (continued). "Therefore TRAF2 and GRK2 co-expression induce proliferation, migration, and invasion of tumor cells, further promoting MMP-9 expression." (PMID 35572966, 2022). "Platelet-treated tumor cells show downregulated E-cadherin levels and upregulated expression of mesenchymal markers such as Snail, vimentin, fibronectin, plasminogen activator inhibitor 1, and matrix metalloproteinase (MMP)-9." (PMID 35936717, 2022). "In cancers, MMP-9 might have a greater impact on the surround of tumor than on the cancer cells themselves, resulting in a deeper involvement in cancer growth." (PMID 36289761, 2022). "However, the depletion of MMP9 make the tumour cells more invasive and metastatic, a process that is facilitated by the presence of CD11b+ inflammatory monocytes expressing pro-invasive cathepsin B and the secretion of interleukin-6." (PMID 35216069, 2022). "A study of the molecular mechanism showed that FOXP3 promotes tumor metastasis and invasion might be associated with the upregulation of MMP2 and MMP9 expression." (PMID 36235242, 2022). "TANs impair antitumor immunity and accelerate tumor growth and metastasis through the production of growth factors, chemokines, and inflammatory factors such as matrix metalloproteinase-9 (MMP-9), vascular endothelial growth factor (VEGF), high mobility group box 1 (HMGB1), and interleukin (IL)-17." (PMID 36060811, 2022). "Tumor cells usually express high levels of MMP-9, which supports cell motility during invasion." (PMID 35163668, 2022). "For this reason, the current study was based on the analysis of the molecular links of c-Myc/HIF-1α gene expression as well as on the expression of other markers such as c-Jun, ERK 1/2, pERK 1/2, VEGF, MMP-9, and Bcl-2, which are involved in Cal-27 survival/proliferation and tumor progression." (PMID 35890188, 2022). "However, we do report statistically significantly increased MMP-9 expression in the adjacent non-tumor tissue of invasive tumors (82.5% (67.5–90.0%) vs. 70.0% (50.0–90.0%); p = 0.017) when correlated with the adjacent tissue of non-invasive PTC." (PMID 36551933, 2022). "MMP2 and MMP9 are confirmed as crucial regulators of tumor metastasis." (PMID 35030977, 2022). "Angiogenesis within tumor tissues may be related to the upregulation of MMP-9 expression leading to the release of vascular endothelial growth factor (VEGF)." (PMID 35267781, 2022). "MMP-9 can degrade the extracellular matrix components and promote tumor invasion and metastasis." (PMID 35178444, 2022). "Our results show that a hypoxic environment impairs MMP-9 upregulation in tumor cells." (PMID 35163668, 2022). "Interestingly, a correlation between the MMP-2 and MMP-9 expression between the stroma and tumor suggests that tumor cells affect stroma MMPs deposition in BCC." (PMID 35572966, 2022). "Furthermore, we indicated that the tumor immune microenvironment of MMP9-High SCLC is mainly characterized by a large number of infiltrated activated immune cells as well as activated immune-related pathways." (PMID 35431936, 2022). "Resveratrol further demonstrated impaired cell viability, migration, and invasion in ACHN RCC cells via increased histone acetylation through degradation of proteolytic enzymes MMP-2 and MMP-9, considered key proteins in tumor cells’ ability to disrupt cell-to-cell interaction and remodel tissue." (PMID 35805049, 2022). "Additionally, the Rap1 signaling pathway leads to the induction of MMP 2 and MMP-9 expression, resulting in extracellular matrix degradation, facilitating the invasion of tumor cells." (PMID 35273218, 2022). "MMP-9 is a key enzyme that plays a major role in enhancing tumor cell invasion and migration." (PMID 35840633, 2022).
tumor (continued). "Adenoviral gene transfer of MMP-9 in MCF-7 tumors in nude mice significantly reduced tumor growth and microvessel area, with increased levels of anti-angiogenic endostatin, indicating that MMP-9 can inhibit angiogenesis by the generation of anti-angiogenic factors." (PMID 36741729, 2022). "This suggested that MMP-9 promotes anti-tumor T cell response." (PMID 36741729, 2022). "Moreover, IHC analysis presented that the abundance of MAPK1, CyclinD1, and MMP9 was markedly decreased in tumor tissues from the sh‐circ‐CSNK1G1 group." (PMID 35023214, 2022). "We found that HB-derived exosomal lncRNA NEAT1 induced BMSCs to differentiate into tumor-supporting myofibroblasts by regulating the miR-132/MMP9 axis, which might benefit an innovative therapeutic strategy for the treatment of HB patients." (PMID 35300348, 2022). "The pro-tumor mechanisms include: (a) N2 neutrophils secrete cytokines such as VEGF and TNF to promote tumor angiogenesis; (b) Neutrophils secrete matrix metalloprotein 9 (MMP-9) to degrade type IV collagen of the basement membrane, promoting the infiltration of tumor cells." (PMID 35222443, 2022). "Up-regulation of immunocompetent ligand on the surface of tumor cells may contribute to the possible mechanisms of improved prognosis in patients with MMP9-High SCLC after cisplatin treatment." (PMID 35431936, 2022). "Targeting PDGF receptor signaling, FGF1/FGFR3, FAK pathway, HGF secretion, endoglin, activin A, Wnt2 and fatty acid oxidation, matrix metalloprotease 9 (MMP9) and hedgehog (Hh) signaling could delay tumor growth." (PMID 36139552, 2022). "In addition, NF-κB, Bcl-xL, COX-2, IκBα, and MMP-9 levels in the tumor tissue of parthenolide-injected animals were decreased compared to their levels in the untreated control." (PMID 35805049, 2022). "MMP9 plays a central role in tumor progression, especially for cell proliferation and invasion." (PMID 35371977, 2022). "We, therefore, measured the gelatinases MMP2 and MMP9 in tumour tissue and supernatants from BMDM." (PMID 33758004, 2022). "In addition, GNP can inhibit the expression and activity of MMP-9, which can mediate tumor metastasis." (PMID 35954126, 2022). "They found that interactions between CD44 and MMP9 promoted the proteolytic activity of MMP9 against type IV of collagen, which correlated with cell invasiveness and enhanced tumor growth in vivo, and disruption of the CD44–MMP9 complex reduced the migratory potential of cancer cells." (PMID 35406619, 2022). "The expression of MMP-9 was related to the clinical stage in eight tumors, suggesting that MMP-9 may be involved in tumor metastasis." (PMID 35178444, 2022). "Two NET-associated proteases, NE and matrix metalloproteinase 9 (MMP9), can cleave and remodel laminin to reveal an epitope that can subsequently activate FAK/ERK/MLCK/YAP signaling, eventually activating and awakening dormant tumor cells." (PMID 35747797, 2022). "These long-lived immune cells exert their regulatory functions in immunity and inflammation by producing key inflammatory mediators, such as tryptase, VEGF, IL-10, TGF-β1, and MMP9, and the relevant data of their anti-tumor or pro-tumor features have been reported." (PMID 35874749, 2022). "Furthermore, inhibition of MMP9 promoted the therapeutic efficacy of PD-1 blockade, with a marked reduction of tumor burden and extension of survival time." (PMID 35280982, 2022). "Besides, MDSCs were observed to produce VEGF, bFGF, Bv8, and MMP9 to promote tumor progression by influencing the tumor microenvironment and tumor angiogenesis." (PMID 35669436, 2022). "In addition, α2β1 integrin was shown to promote OC cell invasion by increasing matrix metalloproteinase (MMP)-2/MMP-9 activation, thereby disaggregating tumor cell spheroids and enhancing cell proliferation." (PMID 34689222, 2022). "Additionally, by releasing MMP-9, these neutrophils were suggested to promote further activation of TGFβ in tumor microenvironment." (PMID 35158807, 2022).